DRD3 (dopamine receptor D3)
Diseases named in the same sentence as DRD3 in open-access papers (continued):
Sharing a sentence is not in itself a finding about the gene and the disease.
bruxism (2 papers, 2020 to 2025). Excessive clenching of the jaw and grinding of the teeth. "Variations in genes like 5HTR2A, DRD2, DRD3, ANKK1, COMT, MMP9, ACTN3, and ANKK1 are linked with the susceptibility to Bruxism." (PMID 40291793, 2025). "Motivated by the evidence of a genetic component to bruxism, association studies with common genetic variants have been conducted, suggesting an association exists between genes and bruxism (dopamine receptor D genes DRD2, DRD3, DRD5, and the 5-hydroxytryptamine receptor 2A gene, HTR2A)." (PMID 32471213, 2020).
Hyperammonemia (2 papers, 2016 to 2017). An increased concentration of ammonia in the blood. "Our study not only adds a new sensing and output pathway for DRD3 that bridges ammonia sensing and autophagy induction, but also provides potential mechanisms for the clinical consequences of hyperammonemia in brain damage, neurodegenerative diseases and tumors." (PMID 27077655, 2016).
melanoma (2 papers, 2022). A malignant, usually aggressive tumor composed of atypical, neoplastic melanocytes. "We observed that the deficiency of Drd3 (the gene encoding DRD3) in CD8+ T-cells limits their in vivo expansion, leading to an impaired anti-tumour response in a mouse melanoma model." (PMID 36428964, 2022). "Here, we found that DRD3 signalling on CD8+ T-cells potentiates the anti-tumour immune response in a melanoma mouse model." (PMID 36428964, 2022). "Thus, our results provide genetic and pharmacologic evidence indicating that DRD3 favours the production of IL-2 by CD8+ T-cells, which is associated with higher expansion and acquisition of effector function of these cells, promoting a more potent anti-tumour response in a melanoma mouse model." (PMID 36428964, 2022). "DRD2, DRD3, DRD5, and all identified TAARs were significantly downregulated in melanomas compared to nevi samples with the most drastic changes noted in TAARs (p < 0.05)." (PMID 35053262, 2022). "Following mined data, all dopamine receptors were detected in melanomas; among them DRD1 in 33.8%, DRD2 in 11.3%, DRD3 in 4.5%, DRD4 in 62.4%, and DRD5 24.1% of samples." (PMID 35053262, 2022).
nicotine dependence (2 papers, 2014 to 2022). Physical and psychological dependence on nicotine. "The expression of the T allele of the DRD3 rs6280 polymorphism was associated with lower levels of nicotine dependence and lower cigarette consumption and years of smoking." (PMID 35455685, 2022). "The expression of the T allele of the DRD2 rs1800497 and DRD3 rs6280 polymorphisms significantly correlated with a lower level of nicotine dependence and lower use of cigarettes." (PMID 35455685, 2022). "Logistic regressions on the associations of lifetime DSM-IV nicotine dependence (ND)a and the DRD3 variant rs2399496 with lifetime DSM-IV major depressive disorder (MDD) b (N = 1296)." (PMID 24927283, 2014). "Our results further suggest that nicotine dependence may potentiate the influence of the DRD3 genetic variant on MDD." (PMID 24927283, 2014). "We hypothesized that the ANKK1-DRD2 rs1800497, DRD3 rs6280, COMT rs4633, and OPRM1 rs1799971 polymorphisms, together with the 5-HTTLPR genotype, could be involved in the smoking habits and nicotine dependence in patients with treatment-resistant psychiatric disorders." (PMID 35455685, 2022).
opiate dependence (2 papers, 2017 to 2024). Disorders related or resulting from abuse or mis-use of opioids. "However, in contrast to the increases in DRD3 expression in rodents after alcohol and cocaine exposure, a very recent study demonstrated that heroin exposure decreased DRD3 expression, possibly explaining the apparent reduced efficacy of GSK598809 in those with a primary opiate dependence." (PMID 28042871, 2017).
Visual hallucination (2 papers, 2019 to 2022). Visual perception in the absence of a visual stimulus. "A recent study in Slovenia indicated that PD patients carrying at least one DRD3 rs6280 C allele and CC homozygotes displayed more frequently levodopa-induced visual hallucinations compared to those not carrying this allele." (PMID 35741861, 2022).
acute myeloid leukemia (1 paper, 2023). Acute myeloid leukemia (AML) is a group of neoplasms arising from precursor cells committed to the myeloid cell-line differentiation. "For instance, DRD3 is only expressed in glioblastoma and is expressed at lower levels than in a healthy brain, while DRD4 is overexpressed only in acute myeloid leukemia (AML)." (PMID 37509555, 2023).
airways allergy (1 paper, 2019). "On the other hand, we have recently found that DRD3 deficiency results in exacerbated Th2-mediated airways allergy in response to house-dust mite derived antigens." (PMID 31810491, 2019).
alcohol abuse (1 paper, 2022). The use of alcoholic beverages to excess, either on individual occasions ("binge drinking") or as a regular practice. "Szczepankiewicz and colleagues investigated the possible relationship between polymorphisms in the four dopamine receptor genes (−48 A/G in DRD1, −141 C ins/del in DRD2, 9 Ser/Gly in DRD3, and −521 C/T in DRD4) and the comorbidity of alcohol abuse in bipolar patients." (PMID 35893041, 2022).
Apathy (1 paper, 2023). Apathy is a quantitative reduction of interest, motivation and the initiation and persistence of goal-directed behavior, where often the accompanying emotions, thoughts, and social interactions are also diminished. "We found that apathy and risk type of DRD3 polymorphism are interactive risk factors for the severity of ICB." (PMID 37968562, 2023). "Patients with the DRD3 risk type had reduced dopamine synthesis capacity in the putamen and limbic striatum, apathy was associated with reduced dopamine synthesis capacity in the limbic striatum." (PMID 37968562, 2023). "In sum, our findings suggest that apathy and the DRD3 risk variant interact to confer a synergistic risk for the severity of ICB." (PMID 37968562, 2023). "The distribution of ICB, apathy and DRD3 polymorphism was as follows: 23 patients presented at least one ICB and 15 of them had multiple ICBs." (PMID 37968562, 2023). "Future research should explore the potential mechanisms underlying the interaction between apathy and the DRD3 risk variant, as well as the role of other genetic and environmental factors in the pathogenesis of ICB." (PMID 37968562, 2023). "With this in mind, we investigated how ICB expression is explained by apathy and DRD3 polymorphisms and their effects on grey matter volume and dopamine synthesis capacity." (PMID 37968562, 2023). "Apathy and the DRD3 polymorphism were interactive risk factors for ICB severity." (PMID 37968562, 2023). "Indeed, apathy and the DRD3 risk type were associated with impaired function and structure of the striatum." (PMID 37968562, 2023). "We hypothesised that apathy and the DRD3 polymorphism might be synergistic determinants for ICB severity." (PMID 37968562, 2023). "We report that apathy was linked to atrophy of the bilateral putamen and this effect was independent of the DRD3 polymorphism." (PMID 37968562, 2023). "We further found that the dopamine synthesis rate in the limbic striatum was reduced in patients with apathy independent of the DRD3 polymorphism." (PMID 37968562, 2023).
asthenia (1 paper, 2023). Clinical sign or symptom manifested as debility, or lack or loss of strength and energy. "The incidence of akathisia was higher in DRD3 rs6280 Ser/Ser homozygotes vs. Gly allele carriers and asthenia appeared more often in DRD2 rs1799732 G/- subjects vs. G/G homozygotes." (PMID 36873203, 2023).
astrocytoma (1 paper, 2009). "In contrast, the DRD3 was much more inducible than DRD4 in astrocytoma cells, and its mRNA levels were highly elevated already after 24 hr hypoxia." (PMID 19653907, 2009). "One can speculate that the duration of hypoxic treatment (48 hrs) might not have been enough for protein synthesis, although DRD3 mRNA levels were elevated already upon 24 hrs incubation under hypoxic conditions in astrocytoma cells." (PMID 19653907, 2009).
Autoimmunity (1 paper, 2021). The occurrence of an immune reaction against the organism's own cells or tissues. "To confirm the relevance of DRD3 in B cells in CNS autoimmunity, we next generated mice harbouring Drd3 deficiency restricted only to B cells." (PMID 34920747, 2021). "To address the role of DRD3 in the adaptive immune system in the development of CNS autoimmunity we generated chimeric mice bearing Drd3-deficient adaptive immune system and Drd3-sufficient innate immune system." (PMID 34920747, 2021). "Our findings demonstrate that DRD3 in B cells exerts a dual role in CNS-autoimmunity, favouring CNS-tropism of pro-inflammatory B cells with APC-function and promoting CNS-homing of B cells with anti-inflammatory features." (PMID 34920747, 2021). "We next evaluated the role of DRD3 in B cells in a model of CNS autoimmunity that depends on the APC-function of B cells." (PMID 34920747, 2021). "Taken together, these results suggest that DRD3 in B cells plays an important role in the development of CNS autoimmunity, involving different B-cell subsets depending on the nature of the antigen." (PMID 34920747, 2021). "Secondly, when B cells with APC-function are negligible, DRD3-signalling promotes CNS-homing of B cells with anti-inflammatory features and, consequently, dampens the T-cell-mediated autoimmunity." (PMID 34920747, 2021). "Finally, we attempted to determine the mechanism by which DRD3 in B cells exerts a pro-inflammatory effect in the development of CNS autoimmunity in a model dependent of the APC-function of B cells." (PMID 34920747, 2021). "Here we addressed the role of DRD3 in the adaptive immune system in CNS autoimmunity." (PMID 34920747, 2021). "The results show that mice receiving Drd3-deficient or Drd3-sufficient CD4+ T cells developed EAE with similar kinetics and severity, thus ruling out a relevant role of DRD3 in CD4+ T cells in the development of CNS autoimmunity." (PMID 34920747, 2021). "Our findings indicate that DRD3-expression in CD4+ T cells was irrelevant in EAE, whilst DRD3 in B cells exerted fundamental regulatory processes in CNS autoimmunity." (PMID 34920747, 2021). "Using a model of CNS autoimmunity in which the APC-function of B cells is irrelevant, we found another important regulatory effect of DRD3 in the control of B-cell function." (PMID 34920747, 2021). "First, through DRD3, dopamine favours the CNS-tropism in a pro-inflammatory B-cell subset with APC-function, thus contributing to the re-stimulation of encephalitogenic effector CD4+ T cells and thereby reinforcing CNS autoimmunity." (PMID 34920747, 2021). "Here, we provide in vivo evidence using genetic approaches demonstrating that DRD3 in B cells mediates the upregulation of CXCR3 and α4-integrin, thus affecting the recruitment of important B-cell subsets into the CNS upon the development of CNS autoimmunity." (PMID 34920747, 2021). "Using these chimeric mice, we first attempted to determine the relevance of DRD3 in B cells in CNS autoimmunity in a model that does not depend on the APC-function of B cells." (PMID 34920747, 2021).
cerebral palsy (1 paper, 2018). A group of disorders affecting the development of movement and posture, often accompanied by disturbances of sensation, perception, cognition, and behavior. "The results indicated that there was a statistically significant association between a polygenic dopamine gene score reflecting the collective effects of five dopamine gene polymorphisms (COMT, DAT, DRD1, DRD2, and DRD3), and CIMT outcome in 33 children with spastic unilateral cerebral palsy." (PMID 29339100, 2018).
cholangiocarcinoma (1 paper, 2022). A carcinoma that arises from the intrahepatic biliary tree (intrahepatic cholangiocarcinoma) or from the junction, or adjacent to the junction, of the right and left hepatic ducts (hilar cholangiocarcinoma). "DRD3 had been reported that its expression was lower in cholangiocarcinoma cell lines SG231 and CCLP-1, which was consisted with our finding." (PMID 36456906, 2022).
chondrosarcoma (1 paper, 2019). A malignant cartilaginous matrix-producing mesenchymal neoplasm arising from the bone and soft tissue. "Associations of DAXX, DRD3, and DISC1 expression with the clinicopathological characteristics of chondrosarcoma." (PMID 31850367, 2019). "Associations of DAXX, DRD3, and DISC1 expression and clinicopathological characteristics with overall survival in patients with chondrosarcoma, as determined by multivariable Cox regression." (PMID 31850367, 2019). "In competing-risks regression analysis, differentiation (P = 0.005), metastasis (P = 0.014), invasion (P = 0.028), AJCC stage (P = 0.003), Enneking stage (P = 0.036), and DAXX (P = 0.039), and DRD3(P = 0.019) expression were independent predictors of death from chondrosarcoma." (PMID 31850367, 2019). "In this study, the expression and clinicopathological significance of the mental health–related proteins DAXX, DRD3, and DISC1 in chondrosarcoma tissue samples were examined, over an 84-months follow-up period." (PMID 31850367, 2019). "Relationships of DAXX, DRD3, and DISC1 expression and clinicopathological characteristics to average survival in patients with chondrosarcoma." (PMID 31850367, 2019). "In immunohistochemical analysis, the rates of positive DAXX, DRD3, and DISC1 expression were significantly higher in chondrosarcoma than in osteochondroma tissue (P < 0.01)." (PMID 31850367, 2019). "DAXX, DRD3, and DISC1 expression in chondrosarcoma and osteochondroma." (PMID 31850367, 2019).
cognitive decline (1 paper, 2021). "Other side-effects such as cognitive decline, visual hallucinations and daytime sleepiness have been implicated in various polymorphisms of the COMT, DRD2, DRD3, HOMER1 and BDNF genes, but lack consistency in the results to consider current clinical implementations." (PMID 34281267, 2021).
COVID-19 (1 paper, 2021). A disease caused by infection with severe acute respiratory syndrome coronavirus 2. "Salmeterol targets on seven non-n-COV host proteins (ADRB1, ADRB2, ADRB3, AOX1, DRD3, KCNH2, and THPO), meaning that it may not act on COVID-19 via directly targeting COV host proteins." (PMID 34539756, 2021).
cyst (1 paper, 2023). A sac-like closed membranous structure that may be empty or contain fluid or amorphous material. "Bromocriptine, amisulpride, and mirtazapine were all shown to target Drd3 specifically, and therefore may be particularly effective in cyst reduction and cell proliferation by HDAC5 nuclear export." (PMID 37217845, 2023).
diabetes (1 paper, 2018). "Although there is a report indicating that DRD3 is associated with diabetes in human, the exact mechanism has not been elucidated so far." (PMID 30131871, 2018).
Dystonia (1 paper, 2021). An abnormally increased muscular tone that causes fixed abnormal postures. "As a second example, the molecule Chembl372020 [(S)-7-Dipropylamino-5,6,7,8-tetrahydro-indolizine-3-carbonitrile] is linked to two targets/genes, DRD3 (dopamine receptor D3) and DRD2 (Dopamine receptor D2), both involved in dystonia." (PMID 34819133, 2021). "It means that the molecule is significantly involved in dystonia through DRD3 and DRD2 genes." (PMID 34819133, 2021).
endometrial cancer (1 paper, 2021). Primary or metastatic malignant neoplasm involving the endometrium (mucous membrane that lines the endometrial cavity). "In addition, high DRD3 levels in endometrial cancer are associated with increased activity of miR-4640-5p and miR-221-5p, which are involved in tumor progression by regulating proliferation and metastasis." (PMID 34768458, 2021). "In contrast, DRD5 expression was decreased, while DRD2 and DRD3 levels were significantly increased in endometrial cancer." (PMID 34768458, 2021). "Expression of CXCL12, OPRK1, DRD5, COMT, DRD2, and DRD3 proteins was assessed in the serum of endometrial cancer patients and control group using ELISA." (PMID 34768458, 2021). "It has been observed that as endometrial cancer progresses, expression of CXCL12, GNAL, OPRK1, DRD2, and DRD3 increases while DRD5 and COMT levels are gradually reduced." (PMID 34768458, 2021).
essential tremor (1 paper, 2022). A relatively common disorder characterized by a fairly specific pattern of tremors which are most prominent in the upper extremities and neck, inducing titubations of the head. "Interestingly, linkage analysis of genes associated with essential tremor identified four loci: chromosome 3q13 (ETM1), 2p22-p25 (ETM2), 6p23 (ETM3), and 5q35, among which ETM1 contains the DRD3 gene encoding D3 receptors." (PMID 35784764, 2022). "In addition, DRD3-Gly (Ser9Gly variant), which shows a greater affinity for dopamine than the non-mutated form, is reportedly associated with the risk of essential tremor." (PMID 35784764, 2022).
head and neck cancer (1 paper, 2022). A primary or metastatic malignant neoplasm affecting the head and neck. "In support of this, a study performed with human samples obtained from head and neck cancer showed that 10 nM dopamine (which should stimulate DRD3 selectively) increases the migration of T-cells towards autologous tumours." (PMID 36428964, 2022).
hearing loss (1 paper, 2015). "This correlates well with the current study in which DRD3 gene expression is significantly decreased after hearing loss." (PMID 26257610, 2015).
hepatocellular carcinoma (1 paper, 2022). A malignant tumor that arises from hepatocytes. "However, the role of dopamine receptor D3 (DRD3) in hepatocellular carcinoma (HCC) remains unclear." (PMID 36456906, 2022).
liver cancer (1 paper, 2022). An epithelial or non-epithelial malignant neoplasm that arises from the liver. "It has been reported that DRD2 agonists can effectively inhibit the proliferation and metastasis of HCC cells, although there are still no reports on the effects of DRD3 on liver cancer, including the prognosis and biological behavior of HCC." (PMID 36456906, 2022). "This study aims to explore whether DRD3 can be used to predict the prognosis of HCC patients and to evaluate its effect on liver cancer cells in order to preliminarily reveal the role of DRD3 in the occurrence and development of liver cancer and lay a foundation for further research in the future." (PMID 36456906, 2022).
lung carcinoma (1 paper, 2018). "In LUAD of Pan-Lung Cancer cohort, mutations in GMPPA, DNAJC2, and MMRN2 showed significant negative associations with survival of patients while mutations in DRD3 and SETX showed significant positive association with survival." (PMID 30419062, 2018). "In LUAD of Pan-Lung Cancer cohort, mutations in DNAJC2, GMPPA, MMRN2, DRD3, and SETX were significantly associated with survival status, and those in DNAJC2, MMRN2, and SETX were significantly associated with overall survival." (PMID 30419062, 2018).
Obesity (1 paper, 2013). Accumulation of substantial excess body fat. "Interestingly, a third group of genes (CPE, NPY5R, DRD3, TAS2R38, SLC18A1, G6PC3, NPY1R, and VLDLR) was highly associated with both neurological and obesity concepts." (PMID 23544116, 2013).
pancreatic cancer (1 paper, 2018). "In addition, D2-like DRD2 and DRD3 are associated with the scaffold protein GIPC and it has been evidenced that GIPC induced autophagy in pancreatic cancer cells." (PMID 29786666, 2018).
Sepsis (1 paper, 2024). Sepsis is defined as life-threatening organ dysfunction caused by a dysregulated host response to infection. "In comparison to sepsis-induced neuroinflammation, lack of DRD3 dopaminergic signaling in LPS-induced mouse neuroinflammation, increased the expression of the anti-inflammatory mediator Fizz1 in glial cells and increased M1-to-M2 ratio, eventually alleviating neuroinflammation." (PMID 39497013, 2024).